S100A14 (S100 calcium binding protein A14)
Diseases named in the same sentence as S100A14 in open-access papers (continued):
Sharing a sentence is not in itself a finding about the gene and the disease.
cancer (continued). "Several studies have used immunohistochemistry to examine the prognostic potential of S100A14 in different human cancers." (PMID 31105881, 2019). "S100A14 (also known as Breast Cancer Membrane Protein 84) is one of the youngest members of the S100 protein family and has recently gained significant attention in cancer research." (PMID 31105881, 2019). "In contrary, the higher expression of S100A14 in carcinomas from other organs such as ovary, breast, cervix, lung and liver seem to predict poorer survival." (PMID 31105881, 2019). "It is interesting to note that higher or positive S100A14 expression in the carcinomas of gastrointestinal tract was found to be correlated with better patient survival." (PMID 31105881, 2019). "For example, the over-expression of S100A2, S100A3, S100A6, S100A8/A9, S100A11 and S100A14 have been documented in several cancer types." (PMID 30018736, 2018). "There have been some reports regarding the contribution of S100A14 functions to the malignant nature of cancer cells." (PMID 25884418, 2015). "TPA has been reported to promote cancer cell motility through regulating the expression and function of S100A14, cyclooxygenase-2 (COX-2) or matrix metalloproteinase-9 (MMP-9)." (PMID 25915860, 2015). "S100A14 expression is up-regulated in cancers of the lung, breast, and uterus, whereas it is down-regulated in tumors of the colon, kidney, and rectum." (PMID 25884418, 2015). "S100A14 gene was found useful for detection of circulating tumor cells (CTCs) in peripheral blood of advanced cancer patients." (PMID 21559403, 2011). "However, a significant (p < 0.05) positive correlation between ESR1 and S100A14 gene expression was found in Basal and Her2 cancer patients, but such a correlation was significantly (p < 0.05) negative in Luminal A and Luminal B patients." (PMID 39594999, 2024). "In CRC, emerging evidence suggests that S100A14 might influence cancer progression through its interactions with various signaling pathways, impacting cellular proliferation, apoptosis, and migration." (PMID 39205741, 2024). "The higher levels of S100A2, S100A11, and S100A14 transcript in the eight cancer cell lines than in the HPNE control cell line suggest that these three S100s might modulate the behavior of the cancer cells." (PMID 37627239, 2023). "Genes with no significant expression in the majority of the normal donors and exhibiting expression patterns associated with a particular cancer type were 16, among them AGR2, S100A14, S100A16, and FABP1 identified as those with the highest discrimination power between cases with cancers and donors." (PMID 36428760, 2022). "S100A14 has a potential to be clinically useful as prognostic biomarker in several cancer types." (PMID 34530774, 2021). "S100A14 plays an important role in the occurrence and development of various human cancers." (PMID 34804125, 2021). "Several studies have shown that tumor-derived exosomes can facilitate tumor progression and metastasis 22-24, we then assessed whether S100A14 protein is present in cancer cell exosomes." (PMID 32483412, 2020). "Given the critical roles of CCL2 and CXCL5 in recruiting TAMs to neoplastic tissue, thereby contributing to cancer metastasis 30, 31, we investigated whether S100A14 plays a key role in orchestrating the recruitment of macrophages through CCL2 and CXCL5." (PMID 32483412, 2020). "In addition, several studies indicate that the expression pattern of S100A14 has a potential to be clinically useful as prognostic biomarker in several cancer types." (PMID 31105881, 2019). "Of interest, S100A14 seems to have seemingly opposite functions in malignancies arising from the gastrointestional tract (tissues rich in epithelial components) compared to cancers in the other parts of the body (tissues rich in mesenchymal components)." (PMID 31105881, 2019).
cancer (continued). "However, in parallel to the differential expression pattern and sub-cellular localization in different cancer types, the S100A14-mediated functions seem to be specific with respect to cancer types." (PMID 31105881, 2019). "Further molecular characterization of S100A14 mediated tumor suppressive functions might contribute to the better understanding of cancer biology and provide opportunity for S100A14 based therapeutics." (PMID 31105881, 2019). "Results from the in vitro and in vivo functional studies in several cancer types indicate that S100A14 might be useful as a therapeutic target for the treatment of malignancies." (PMID 31105881, 2019). "Both authors found predominant cytoplasmic S100A14 staining in carcinoma cells." (PMID 31105881, 2019). "Fourth, we did not obtain detailed cancer metastasis and survival information, which further restricted the analysis of S100A14 rs11548103 G>A polymorphism in ESCC progression and prognosis." (PMID 29156846, 2017). "However, the molecular mechanism of S100A14 involvement in GC cell differentiation and cancer metastasis remains poorly understood." (PMID 28726786, 2017). "We report here for the first time that S100A14 and S100A16, which have been previously shown to be associated with cancer cell invasion, are abundant in blastocysts and appear to be localized to the trophectoderm, consistent with a role in the invasiveness of the trophoblast during implantation." (PMID 27241529, 2016). "S100A14-positive staining was mainly localized to the cytoplasm and cytomembrane in cancer cells." (PMID 27270322, 2016). "We have focused on the detection of novel biomarkers of cancer progression including of invasion and metastasis based on experimental studies and have identified the S100 family proteins S100A14 and S100A16 as important candidate molecules for the regulation of metastatic disease." (PMID 25884418, 2015). "Our findings indicate a novel molecular mechanism of S100A14 that may promote cancer invasion by binding to actin to activate cell movement." (PMID 25884418, 2015). "Differential expression of S100A14 has been reported in a number of human cancers." (PMID 24086685, 2013). "In contrary, no appreciable effect was observed both on the mRNA and the protein levels of S100A14 when S100A16 was over-expressed in cancer cell-lines, suggesting a unidirectional regulation between S100A14 and S100A16 where only S100A14 regulates protein abundance of S100A16." (PMID 24086685, 2013). "Having observed an increase only in the S100A16 protein and not in S100A16 mRNA expression when S100A14 was over-expressed in the cancer cells, we speculated that S100A14 might be involved in the regulation of S100A16 protein degradation." (PMID 24086685, 2013). "However, there was no increase in the mRNA expression levels of S100A16 in these S100A14 over-expressing cancer cell-lines." (PMID 24086685, 2013). "However, the precise mechanism and molecular signaling of S100A14 in human cancer is not fully understood." (PMID 24086685, 2013). "We found that S100a14 was increased in the organoids derived from PDAC tumors compared to the normal organoids, which is consistent with the increased expression observed in murine cancer cells and patient cancer cell lines and was linked to poor overall survival." (PMID 36828915, 2023). "Interestingly, a nuclear or cytoplasmic localization of S100A14 was reported in carcinoma cells." (PMID 31105881, 2019). "However, to date, the mechanism of its cell membrane localization and the precise role of S100A14 in human cancer remain unclear and controversial." (PMID 25884418, 2015).
cancer (continued). "Other studies have also shown that PTGDS, GREM1, LAMA4, S100A14, PREX2, and GLS2 have potential value in promoting cancer progression and predicting cancer prognosis." (PMID 37306872, 2023). "S100A14 is overexpressed in human PDAC cell lines and tissues, and its expression level is positively correlated with advanced cancer stages and negatively correlated with the survival time of PDAC patients." (PMID 34527585, 2021). "Compared with para-cancer tissues, the expression levels of S100A4/S100A6/S100A10/S100A11/S100A13/S100A14/S100P were higher in HCC tissues, while the expression levels of S100A8/S100A9/S100A12 were decreased in tumor tissues." (PMID 33815482, 2021). "Using the Genomics of Drug Sensitivity in Cancer (GDSC) and The Cancer Genome Atlas (TCGA) databases, we identified 4 biomarkers (CYTH3, GALNT3, S100A14, and ERI1) to predict cisplatin sensitivity." (PMID 34676288, 2021). "Expression of LSR (A), S100A14 (B) and DPYSL3 (C) in breast, prostate and others (retinal pigment, liver, colon and esophageal) cancer cell lines from QN + SVA normalized integrated data." (PMID 28651527, 2017). "To analyze the functional roles of S100A14 and S100A16 in cancer cells, we examined the cellular behavior of MCF7 and SK-BR-3 cells transfected with S100A14 and S100A16 specific siRNAs." (PMID 25884418, 2015). "Similar to S100A14, recent studies have shown differential expression of S100A16 in different human malignancies, suggesting a role of this protein in human cancers." (PMID 24086685, 2013). "In this study, we show that S100A14 interacts with another S100 protein, the S100A16, and modulates its expression in human cancer cell lines." (PMID 24086685, 2013). "The biological significance of the interaction between S100A14 and S100A16 was next examined by over-expressing S100A14 in a number of human cancer cell-lines (CaLH3, VB6, H357, OSCC1 and HeLa) using a retroviral mediated gene expression strategy." (PMID 24086685, 2013). "Further, over-expression of S100A14 was found to increase the S100A16 protein level but not the mRNA expression levels in the human cancer cell lines studied, indicating a role for S100A14 in possible post-transcriptional regulation of the S100A16 protein." (PMID 37509106, 2023). "The data showed that S100A4, S100A14 and S100A16 were significantly higher in PDAC tissues compared with their counterparts, but the protein level of S100A2, S100A6 and S100A10 were similar between cancer tissues and their counterparts." (PMID 34530774, 2021). "There have been many reports of S100A14 expression in a variety of cancers, whereas S100A16 has not been well analyzed in clinical cases." (PMID 25884418, 2015). "Hence, it will be a future challenge to examine how S100A14 is involved in the regulation of S100A16 expression and to understand the functional significance of S100A14/A16 heterodimer in normal and the cancer cells." (PMID 24086685, 2013). "Given the prominent role of S100A14 on cell proliferation and apoptosis, therapeutic intervention targeting the S100A14 and RAGE signaling pathway may provide a novel approach for cancer therapy." (PMID 21559403, 2011). "In contrast, at the rear of this front, cancer cells including S100A14-positive and-negative cells appear to follow the migrating leader cells by maintaining cell-cell attachments, whether they express S100A14 protein or not." (PMID 25884418, 2015).
tumor (45 papers, 2008 to 2026). "Collectively, these results indicate an association between S100A14 expression and the cytotoxic tumor microenvironment in MSI-H tumors." (PMID 40806532, 2025). "Functionally, S100A14 has been linked to a variety of cellular activities related to carcinogenesis, such as cell proliferation and apoptosis, tumor cell migration and invasion, and keratinocyte differentiation." (PMID 40869249, 2025). "High S100A4 expression is linked with tumor aggressiveness, whereas low S100A14 expression is associated with advanced disease stages and increased metastasis." (PMID 39205741, 2024). "Levels of S100A14 have been found to be lower in cancerous tissue and associated with metastasis, suggesting a tumor suppressor function." (PMID 38099574, 2023). "Bioinformatics analysis revealed that nPKC-θ directly regulates genes involved with mesenchymal, metastatic CSC-like signatures and tumor markers such as S100A14 (a marker associated with metastasis)." (PMID 35326747, 2022). "Exploration of the single-cell dataset CRA001160 further demonstrated that high expression of S100A14 was associated with reduced infiltration of CD8 + T cells in tumor tissue." (PMID 35953822, 2022). "Specifically, loss of S100A14 expression at the tumor-invading front was found to be associated with poor differentiation and worse prognosis." (PMID 36114176, 2022). "Meanwhile, S100A14 has been reported to be differentially expressed in various human malignancies and implicated in tumorigenesis and tumor progression." (PMID 35953822, 2022). "Conversely, the mRNA expression of S100A14, IL1A, CCL2, CXCL3 and CXCL5 in tumor tissues derived from S100A14-deficient mice was significantly reduced compared with those from their WT counterparts." (PMID 32483412, 2020). "Functionally, S100A14 has been linked to the regulation of a number of cellular functions related to carcinogenesis, such as cell proliferation and apoptosis, tumor cell migration and invasion, and keratinocyte differentiation." (PMID 31105881, 2019). "In this study, we found that decreased S100A14 expression was associated with poor differentiation, tumor depth, lymph node status and metastasis." (PMID 28726786, 2017). "Immunohistochemical staining demonstrated that S100A14 expression was associated with advanced stage (P < 0.001) and poor tumor grade (P < 0.001)." (PMID 24939856, 2014). "S100A14 has been implicated in tumor progression, yet its regulatory hierarchy and functional interplay in PC remain unclear." (PMID 41799516, 2026). "Finally, tumor mutation burden analysis and immunophenoscore algorithm revealed that patients with high S100A14 expression had a higher probability of responding to immunotherapy." (PMID 35953822, 2022). "Furthermore, S100A14 immunoreactivity significantly correlated with features also associated with poor prognosis, including tumor stage (P < 0.001), histologic subtype (P = 0.004), and tumor grade (P < 0.001)." (PMID 24939856, 2014). "Herein, we first revealed that S100A14 is a critical molecular mediator of tumor-derived exosomes (EVs)-driven BrM." (PMID 41961478, 2026). "Analyses of lung ADC cases have shown frequent upregulation of S100A14 in tumor tissues and serum correlating strongly with poor differentiation, metastasis, advanced disease stage, smoking history, EGFR mutations, and unfavorable patient outcomes." (PMID 41164170, 2025). "The GSE24550 dataset, comprising 41 MSS, 10 MSI-Low (MSI-L), and 14 MSI-H CRC samples, showed tumor S100A14 expression level distributions based on microsatellite instability status." (PMID 40806532, 2025).
tumor (continued). "The expression of S100A4 and S100A14 proteins was assessed using immunohistochemistry, and their correlation with clinico-pathological features and tumor location was evaluated using statistical analysis." (PMID 39205741, 2024). "Results show that the expression levels of S100P and S100A14 were significantly (p < 0.001) higher in the tumor tissue compared to the normal tissues." (PMID 39594999, 2024). "This study aims to analyze the general and medical characteristics of CRC patients, with a particular focus on the expression patterns of S100A4 and S100A14 proteins and their correlation with tumor location and various clinical parameters." (PMID 39205741, 2024). "S100A14, which has been shown to exert tumor-suppressive effects in gastrointestinal cancers, was upregulated in a dose-dependent manner in HCT116-GFP cells while a dose-dependent decrease was observed in PBMCs." (PMID 36803614, 2023). "In contrast, while S100a14 mRNA was significantly increased in YFP + tumor organoids compared to YFP + normal organoids, its expression was decreased in solid organoids." (PMID 36828915, 2023). "Firstly, dimensionality reduction clustering and expression distribution analysis of S100A14 showed that S100A14 was mainly expressed in tumor cells, and the expression of S100A14 in tumor cells was significantly higher than that in normal ductal cells." (PMID 35953822, 2022). "In this study, we found that low expression of ZHX2 led to upregulation of S100A14, which in turn promoted cell migration, wound healing and lung metastatic tumour formation." (PMID 35151335, 2022). "A joint analysis of TCGA and GTEx databases confirmed the remarkably high expression of S100A14 in tumor tissues." (PMID 35953822, 2022). "Clustered stromal cells corresponded to endothelial cells (positive for PECAM1/CD31, VWF), normal fibroblasts (FN1, EGFL6), tumor-associated fibroblasts (TAFs; PDGFRA, ADH1B), and thymic epithelial cells (TECs; KRT19, S100A14)." (PMID 35869073, 2022). "When HIFU is combined with anti-PD-1, tumor proliferation-related genes such as Wnt7b,S100a14 and Erbb2 are significantly downregulated, and newly released tumor-specific antigens, cytokines, and cell fragments act as agonists of innate immunity." (PMID 36032103, 2022). "S100A14 has been reported to be dysregulated in various types of tumours and involved in the proliferation, apoptosis and signal transduction of tumour cells." (PMID 35151335, 2022). "Subsequently, analysis of single-cell dataset CRA001160 revealed that S100A14 was mainly expressed in tumor cells." (PMID 35953822, 2022). "Meanwhile, the analysis from CPTAC database also indicated that S100A14 was significantly overexpressed in tumor tissue at the protein level." (PMID 35953822, 2022). "Tumor cells were automatically scored for S100A14 expression, and cells in the stroma were also identified automatically through the membrane staining (CD3 + CD8 + cells were considered as CD8 + T cells)." (PMID 35953822, 2022). "Subsequently, according to the S100A14 expression in tumor cells, patients were divided into S100A14 low expression group, S100A14 medium expression group and S100A14 high expression group." (PMID 35953822, 2022). "The machine was designed to automatically segment the tumor cells and score the expression of S100A14 on the tumor cells." (PMID 35953822, 2022). "Knockdown of S100A14 markedly decreased the lung weight, migrated area and number of metastatic tumours compared to those of the shNC-transduced group." (PMID 35151335, 2022). "Similar to these results, the results showed that the expression of S100A14 was significantly upregulated in HCC tissues than in para-tumor tissues." (PMID 33815482, 2021). "Five of the proteins (involucrin, CLCA4, S100A14, Serpin B5 and myosin-11) were found in the Pap test fluid; four of these proteins were also found in either the swab or tumor samples." (PMID 33413078, 2021).